POLE (DNA polymerase epsilon, catalytic subunit)
Diseases named in the same sentence as POLE in open-access papers (continued):
Sharing a sentence is not in itself a finding about the gene and the disease.
tumor (continued). "It is important to note that the presence of a POLE mutation alone is insufficient to classify tumours as ‘POLEmut’, and that classification of tumours with combined POLE mutation and MMRd/MSI depends on the POLE‐score (i.e. genomic correlates) of the POLE mutation." (PMID 31829442, 2020). "POLE/D mutations appear to define a subset of cancers with an ultra-mutated phenotype that are often MSI-low and have been linked with durable responses to PD-1 inhibition in multiple tumor types." (PMID 31258846, 2019). "Indeed, this signature is characteristic of tumours showing both MMR deficiency and POLE loss of function." (PMID 31480372, 2019). "The patients with POLE somatic mutations had a higher tumor mutational burden compared with patients without POLE mutations (P = 1.26e-76)." (PMID 31864301, 2019). "MMRd EC shows a similar increase in tumor-infiltrating lymphocytes as seen in POLE-mutant EC, however, it is associated with negative prognostic factors such as higher histologic grade, presence of LVSI and with older age, and advanced stage (III/IV)." (PMID 31367798, 2019). "One patient with a hotspot POLE-mutated tumour lacked follow-up data and was excluded from the recurrence analysis." (PMID 30917185, 2019). "Interestingly, tumor purity was significantly higher in the CIN tumors than POLE-mutant and MSI tumors (P = 0.002, Wilcoxon rank sum test)." (PMID 31416464, 2019). "It seemed that POLE mutated tumors were not grouped together, likely because POLE mutations have a low overall rate (~1.0%) in the entire PanCanAtlas cohort and, therefore, had a limited weight on clustering of tumor samples." (PMID 30956779, 2019). "Furthermore, we revealed that the somatic mutation of POLE and PTEN represented a primary trigger for tumourigenesis in tumours with defective POLE proofreading ability." (PMID 29880869, 2018). "The only tumor without preferential IS gene conservation enrichment had a POLE mutation, suggesting an alternative mechanism for immune evasion when the mutation burden is exceptionally high." (PMID 30470817, 2018). "Two patients had MSI-H tumors while 1 hypermutant tumor was MSS and harbored a POLE mutation." (PMID 28178681, 2017). "POLE-mutated and MSI tumors have an active TME not only for the high number of TILs, but also for the huge amount of tumor specific neo-antigens, generated by genetic alteration acquired due to impaired DNA replication fidelity (POLE) and defective DNA MMR system (MSI-H)." (PMID 29163851, 2017). "One study reported that other tumor suppressors resulting in MSS tumors, such as MutYH, PolD, PolE, and NTHL1, might be associated with the pathogenesis of CRC in addition to APC gene mutations." (PMID 29237421, 2017). "MMR-deficient and CTNNB1-mutant were considered at intermediate risk, while POLE-mutant tumours and tumours with no specific molecular profile are designated favourable." (PMID 28424422, 2017). "We investigated whether these were related, and found that POLE-mutant ECs display a robust T cell response that corresponds to an enrichment of antigenic tumor neopeptides." (PMID 27141333, 2016).
tumor (continued). "To determine whether POLE EDMs in MSS CRC constitute a tumor type with specific clinical characteristics, we investigated the associations of POLE mutations with major clinical parameters." (PMID 25124163, 2014). "When zooming in on different clinical subgroups, we observed different hazard ratios for patients with POLE-mutated tumors with respect to sex, age, grade, and location of tumor, all of which were, again, not statistically significantly different." (PMID 25124163, 2014). "POLE p.Leu424Val, POLD1 p.Ser478Asn, and POLD1 p.Pro327Leu all map within the proofreading (exonuclease) domain of the respective enzyme, suggesting that deficient proofreading repair during DNA replication is the cause of our patients' tumours." (PMID 23447401, 2013). "The presence of PVs in POLE and POLD1 affecting the exonuclease activity of polymerases ε and δ, respectively, causes uncorrected errors during DNA replication resulting in the highest tumour mutational burden, often exceeding 100 mut/Mb, and referred to as ultra-hypermutator phenotype." (PMID 40237887, 2025). "This scoring system was improved, assessing whether POLE alterations were recurrent in EC within the COSMIC or TCGA databases, since recurrent mutations are more likely to be pathogenic as they are responsible for tumor ultramutation." (PMID 40936703, 2025). "Together, 47 known and 9 previously unknown mutational signatures were identified, of which SBS28 and DBS-CRC5 were associated with POLE mutant MSS CRC, the SBS-CRC1, DBS-CRC3 and ID-CRC1 signatures with MMR, and the DNA MMR SBS44 signature in HM tumours with longer OS." (PMID 39112715, 2024). "Moreover, we found 0.57% of TMB-Hi tumours to have POLE hotspot mutation, but none in CpG hypermutated tumours." (PMID 39026103, 2024). "The data presented here are hypothesis-generating and suggest that non-pathogenic POLE variants may further increase POLE ExoD driver–associated mutation rates and tumor neoantigens." (PMID 38282550, 2024). "Moreover, the tumor of patient 1 with a POLD1 mutation had no POLE mutation associated signature but conversely the POLD1 mutation associate signature." (PMID 39233831, 2024). "None of our responders had POLE/POLD mutations or high tumor mutational burden." (PMID 38378868, 2024). "Two of the 3 tumours with evidence of dMMR (2 with SBS20, SBS26 and hypermutated phenotype) harboured MLH1 somatic mutations which were accompanied by LOH, while the other carried a POLE mutation of unknown significance." (PMID 39009593, 2024). "Interestingly, the severity of the proofreading and fidelity defects observed for POLE variants is not correlated to their frequency detected in cancers, implying that besides proofreading loss, additional mechanisms drive tumor initiation and progression." (PMID 37891003, 2024). "We additionally removed samples in which POLE-exo variant might be a false positive, or might have occurred late during the tumor development (in which case the pattern could be also not visible)." (PMID 36829160, 2023). "Our results not only confirm known associations, such as mismatch repair and POLE gene mutations with high TMB, but also identify significant associations between mutations in the SWI/SNF chromatin remodelling genes ARID1A and SMARCA4 and high TMB in multiple tumour types." (PMID 37821580, 2023). "Previous studies have demonstrated that POLE EDM ECs are characterized by a high prevalence of C > A substitutions, frequently exceeding 20%; a low proportion of small insertion and deletion mutations (indels); and an extremely high tumor mutational burden (TMB > 100 mut/Mb)." (PMID 36765365, 2023).
tumor (continued). "A mutation of POLE, DNA polymerase ε, which has polymerase activity and 3′-5′ exonuclease activity, along with MMR deficiency, will cause a high tumor mutation burden, resulting in the accumulation of mutated genes in cells and the production of tumor neoantigens." (PMID 37370880, 2023). "Similarly, in this report, we presented a case of EC whose tumor was ultra-mutated and dMMR with MSH6 loss may be driven by the somatic POLE T278K mutation and the secondary somatic MSH6 mutations (E1234* and E1322*)." (PMID 36765365, 2023). "In addition, studies on POLE/POLD1 mutations have not been extended to all tumor types, and there are relatively few studies on the morphological and immunohistochemical expression rates of POLE/POLD1-mutated tumors." (PMID 35780178, 2022). "Thus, POLE could function as a biomarker for the early diagnosis, prognosis, immune-excluded tumor microenvironment and response to immunotherapy of HCC." (PMID 35812186, 2022). "Thus, POLE could function as a predictive biomarker for the early diagnosis, aggressive progression, and immune-excluded tumor microenvironment of HCC, especially the for Asian, male, low-risk HCC patients." (PMID 35812186, 2022). "Notably, POLE mutant EC was mostly grade 3 on histologic examination, but some were grade 1 or 2, which underscores the importance of incorporation of the genetic/molecular landscape to histologic characteristics of the tumor to understand the prognosis." (PMID 36358604, 2022). "Moreover, previous studies have revealed a high frequency of recurrence and death among patients with tumors of the TP53abn group and whereas none of the patients carrying a POLE-mutated tumor had recurrence or died." (PMID 34150634, 2021). "Importantly, POLE was involved in the infiltration of the tumor microenvironment of pan-cancer, which sheds novel insights into drug development and may improve the efficiency of clinical therapies." (PMID 34950188, 2021). "Thus, although extensive methylation in MGMT and SFRP2 has a similar feature in terms of association with CRC with KRAS mutations, all POLE-mutant tumours demonstrated extensive methylation in SFRP2, but no methylation in MGMT." (PMID 34034807, 2021). "Furthermore, studies have shown that tumors with MMR defects can also contain other DNA repair defects, such as POLD or POLE mutations, and several immune checkpoint ligands, including PD-1, PD-L1, CTLA-4, LAG-3 and IDO, are also highly expressed in the tumor microenvironment of these patients." (PMID 33968789, 2021). "Moreover, we found that POLE expression in cancers significantly correlated with an immunosuppressive tumor microenvironment, higher intratumoral heterogeneity, and expression of immune checkpoint genes PDCD1, CTLA4, and CD86, possibly mediated via the JAK/STAT and Notch signaling pathways." (PMID 34950188, 2021). "Thus, the genomic characteristics of MSI‐H cancers with a POLE mutation outside the exonuclease domain are similar to those of MSI‐H tumours without a POLE mutation." (PMID 31829442, 2020). "To help characterize the identified variants, we used the TCGA and COSMIC tumor sequencing data to see if those variants, when occurring somatically and in absence of additional somatic POLE/D1 ED variants, caused a hyper/ultramutated phenotype and the POLE/D1 ED-associated signatures." (PMID 32792570, 2020). "The clinical characteristics of patients whose tumours have a POLE mutation are not clear." (PMID 30917185, 2019). "In addition, the definition of pathogenic mutations used to classify a tumour as “POLE mutated” is not yet clearly defined." (PMID 30917185, 2019).
tumor (continued). "In addition, analysis of the non-endometrioid tumours (N = 98) showed that the POLE mutation (N = 7) did not have a significant positive effect on survival." (PMID 30917185, 2019). "However, the tumor was not classified as hypermutated (10.23 mutations/Mb) and had no underlying somatic POLE mutation." (PMID 31638937, 2019). "We prepared one tissue microarray with 22 tumor tissue samples, including seven cases of the P286R site mutation, five cases of the V411L site mutation, six cases of other mutations within POLE exons 9–14, and four cases without exon 9–14 mutations in the POLE gene." (PMID 31552169, 2019). "The POLE-mutated tumours were mostly, but not exclusively, endometrioid and low risk." (PMID 30917185, 2019). "The genomic instability in the POLE-mutated tumours is not due to aneuploidy but rather to the missing controls in DNA replication and therefore reflects a different mechanism; this may be the reason for the missing effect of ploidy on prognostic significance." (PMID 30917185, 2019). "Therefore, we concluded that, based on the two-hit hypothesis, the somatic mutation of POLE and PTEN served as a primary trigger for tumourigenesis in POLE-category tumours." (PMID 29880869, 2018). "Our data also suggest that even tumors with aberrations in both alleles of POLE (‘double hit’-phenotype) or double mutations of POLE do not necessarily differ from counterparts with wildtype alleles or with a mutation in one allele with respect to clinical features of the tumor." (PMID 25124163, 2014). "LOH has not been reported in cancers with somatic POLE mutations, although a few of these tumours have protein-truncating mutations that could act as ‘second hits’." (PMID 23447401, 2013). "Patients carrying mutations in these genes exhibit a highly distinctive phenotype leading clinicians to consider POLE and POLD1 testing not only based on the polyposis phenotype but also on the broader tumor spectrum." (PMID 39661238, 2025). "Specific cancer subtypes, such as POLE-mutant and MMRd ECs, are typically TMB-H neoplasms characterized by immunogenic tumor microenvironments." (PMID 40805123, 2025). "The study revealed MSI tumours with MLH1/PMS2 defects and high-grade POLE-wildtype/MSS tumours expressing high immunogenicity characterized by intense T-cell infiltration, especially at the invasive edge." (PMID 41312167, 2025). "Unique molecular characteristics have been described in neoplasms from defective DNA repair-related polyposis involving the MUTYH, NTHL1, MBD4, MSH3, POLE and POLD1 genes and the MMR genes in CMMRD." (PMID 40237887, 2025). "Studies suggest that POLE-mutant tumors are more immunogenic owing to their high TMB, resulting in increased immune infiltration within the tumor microenvironment, which enhances antitumor immune responses." (PMID 40072110, 2025). "Collectively, we credential POLE as a CIC::DUX4 target and further characterize a functional network through which CIC::DUX4 operates to drive tumor progression and survival." (PMID 40760094, 2025). "A new signature, termed SBS-CRC1, was found in 17 tumours, all MSI or POLE mutant, and correlated with the defective DNA MMR SBS15 signature (r = 0.40, FDR-adjusted P = 7.82 × 10−40)." (PMID 39112715, 2024). "Our analyses of mutations with VAF higher than the one of the POLE/POLD1 mutations and of potential driver genes point towards alterations that could represent new targets whether they occur early during oncogenesis or are selected during the evolution of the tumor." (PMID 39233831, 2024). "Contributions of signatures associated with MMRD (SBS6, SBS15 and SBS26) and concurrent defects in the exonuclease domain of POLE and POLD1 (SBS14 and SBS20) were found in the CMMRD tumors, depending on the affected gene and tumor type." (PMID 39031223, 2024). "The favorable prognosis of POLE-mutant and dMMR subtypes has been suggested to correlate with increased density of CD8+ tumor-infiltrating lymphocytes (TILs) and higher PD-1expression." (PMID 36675305, 2023).
tumor (continued). "Different from MMR-deficient hypermutated CRC, several unique point mutations in the proofreading domain of replicative DNA polymerase epsilon (PolE) were found in these CRC and the tumor is characterized as being microsatellite stable (MSS)." (PMID 35326618, 2022). "The signatures of Ultraviolet (SBS7, P=0.081, Wilcoxon test), POLE (SBS10a/b, P=0.092, Wilcoxon test), MMRdeficiency (SBS15, P=0.550, Wilcoxon test), and BRCA (SBS3, P=0.630, Wilcoxon test) in the tumor are also more enriched but lack statistical significance." (PMID 35515115, 2022). "In summary, EC patients with high TMB showed abundant tumor-infiltrating CD8+ T cells and relatively high levels of PD-L1 expression in tumor cells, which is consistent with data from previous studies on POLE mutant and MSI-H EC." (PMID 36532042, 2022). "The most common tumour types were colorectal, followed by endometrial in POLD1 heterozygotes and duodenal in POLE heterozygotes." (PMID 33948826, 2022). "This study aimed to explore the significance role of POLE in HCC prognosis, clinical treatment and tumor immune microenvironment based on large-scale multiply cohorts." (PMID 35812186, 2022). "To understand better the contribution of hypermutagenesis to tumour development, we have modelled the most recurrent POLE-EDM (POLE-P286R) in Schizosaccharomyces pombe." (PMID 34228709, 2021). "In our study, we found that POLE amplified tumor samples exhibited 50% reduced mutation burden than tumors without POLE amplification in bladder urothelial carcinoma (BLCA) and OV, suggesting that the gain-of-function POLE CNAmp may lead to an increased DDR function in cancer." (PMID 32226530, 2020). "Some of them have been reported to play important roles in the development of tumor proliferation, apoptosis, and metastasis, such as IGF1R, MYBL2, POLE, and DDAH1." (PMID 32923489, 2020). "Despite the absence of tumor hypermutation and POLE-associated mutational signatures, whether the variant is the cause of the cancer aggregation in the family remains to be elucidated, and if so, what is the molecular mechanism underlying its potential causal effect." (PMID 32792570, 2020). "We were able to reconstruct the tumor progression history for the vast majority of CIN tumors (43 out of 46) as well as all of the MSI and POLE-mutant tumors." (PMID 31416464, 2019). "Exome sequencing of the tumor corresponding to the p.V474I variant carrier revealed a slightly higher number of substitutions compared with four POLE wild-type tumors, although the increment was not as high as could be expected taking into account previously reported data." (PMID 28423643, 2017). "We present a renal transplant recipient with metastatic small bowel adenocarcinoma harboring a POLE mutation who was treated with pembrolizumab and achieved a complete metabolic response on PET-CT with negative circulating tumor DNA." (PMID 42311713, 2026). "Of the tumors that formed in shPOLE_1 and shPOLE_2 cohorts, we observed re-expression of POLE in tumor explants suggesting that POLE knockdown was not sustained in these tumors." (PMID 40760094, 2025).